NUMB (NUMB endocytic adaptor protein)
Diseases named in the same sentence as NUMB in open-access papers (continued):
Sharing a sentence is not in itself a finding about the gene and the disease.
pancreatic cancer (6 papers, 2013 to 2025). "Thus, NUMB downregulation has been associated with increased castration-resistant progenitors in prostate cancer, resistance to imatinib in chronic myeloid leukemia, and increased radioresistance in pancreatic cancer." (PMID 36672267, 2023). "NUMB endocytic adaptor protein (NUMB), a cell fate determinant in asymmetric cell division, is strongly correlated with the development and progression of pancreatic cancer." (PMID 34772375, 2021). "The treatment of pancreatic cancer cells with quercetin leads to an increase in let-7c and NUMB endocytic adaptor protein (NUMB) levels." (PMID 33066509, 2020). "In this study, it was proposed that the transcription of NUMB, a Notch inhibitory factor, is activated by let-7c, subsequently inhibiting the expression of Notch and stemness factors in pancreatic cancer cells." (PMID 33066509, 2020). "We also included the down regulation or loss of function scenario of few proteins such as GAS1, SUFU, NUMB, SNO etc. in pancreatic cancer model." (PMID 23935937, 2013). "We measured the expression of key members of the Notch Signaling Pathway (NUMB, DTX4, DTX3L, PSEN1, APH1A, ADAM17 and EP300) in the MiaPaCa-2-miR-148a by qRT-PCR, and compared it with the basal levels of the control pancreatic cancer cell line MiaPaCa-2, expressing very low levels of miR-148a." (PMID 29464088, 2018).
prostate carcinoma (6 papers, 2016 to 2023). A carcinoma that arises from epithelial cells of the prostate gland. "Decreased NUMB levels have also been found to increase the castration-resistant population in prostate cancer cells as a result of the deregulation of the NOTCH and Hedgehog pathways." (PMID 36672267, 2023). "Furthermore, miR-9-5P, has also been shown to increase stem cell growth and metastasis in prostate cancer by negatively regulating NUMB." (PMID 36672267, 2023). "Consistent with Casodex preventing expression of some potentially harmful isoforms in prostate cancer cells, the splicing inclusion of NUMB exon three and TUFT1 exon two were reduced by Casodex (both these exons are normally activated by androgen exposure and ESRP2)." (PMID 31478829, 2019). "As noted in a recent review, NUMB inhibition of Notch activity may serve as a therapeutic target in prostate cancer." (PMID 27506933, 2016). "NUMB (protein numb homologue) is a key regulator of cell fate that controls NOTCH and GLI, which play major roles in prostate cancer." (PMID 29535815, 2018).
cervical carcinoma (5 papers, 2013 to 2025). A carcinoma arising from either the exocervical squamous epithelium or the endocervical glandular epithelium. "In contrast, the association between cytoplasmic NUMB expression and cervical cancer was lost after adjusting for nuclear NOTCH1 expression (β = 2.074, 95% [CI] = –0.358, 4.506, P = 0.094)." (PMID 29721172, 2018). "Besides, cytoplasmic NUMB expression was associated with a decrease in nuclear NOTCH1 expression in cervical cancer samples, suggesting the potential regulation of NUMB over NOTCH1, as previously suggested." (PMID 29721172, 2018). "Even more, we found that premalignant lesions tended to express NUMB in the nucleus which is upregulated in cervical cancer with a cytoplasmic localization." (PMID 29721172, 2018). "Similar tumor-suppressive properties have been observed in cervical cancer, where Interleukin-8 (IL-8) has been shown to downregulate NUMB expression while upregulating IL-8 receptors and extracellular signal-regulated kinase (ERK) signaling, indicating a role in tumor proliferation and migration." (PMID 40296944, 2025). "Our data suggest that the loss of nuclear NOTCH1 but not NUMB might be an independent predictor of malignancy in cervical cancer." (PMID 29721172, 2018). "Another NUMB isoform, but not the NUMB isoform 4, is highly expressed in cervical carcinoma." (PMID 24302991, 2013).
leukemia (5 papers, 2013 to 2017). A malignant (clonal) hematologic disorder, involving hematopoietic stem cells and characterized by the presence of primitive or atypical myeloid or lymphoid cells in the bone marrow and the blood. "The expression of NUMB is frequently lost in several human cancers, including leukemia and lung and brain cancers." (PMID 27506933, 2016). "Quantitative promoter PCR was performed in selected, potential ERG targets genes related to PI3K or leukemia including AR, NUMB, NRG1, and ETS1 in AML A-E, and T-ALL ChIPs." (PMID 23300998, 2013). "We uncovered that only the proximal promoter of NUMB was significantly enriched at least 1.5-fold in 5 of 6 leukemia ChIPs." (PMID 23300998, 2013). "Furthermore, we uncovered DAAM1, a WNT signaling and potent morphogenesis gene, and NUMB as novel putative targets of ERG in leukemia." (PMID 23300998, 2013). "In addition, three integration sites of the RV vector were found within cancer-related genes (Klf5, NUMB, and FHIT), all of which are associated with leukemogenesis or leukemia progression." (PMID 23990961, 2013). "Recent studies suggest that the translation of NUMB mRNA, which is a known target of MSI1, inversely correlates with MSI2 expression in leukemia." (PMID 23667531, 2013).
ovarian carcinoma (5 papers, 2021 to 2025). A malignant neoplasm originating from the surface ovarian epithelium. "NUMB knockdown has been shown to enhance cisplatin sensitivity in ovarian cancer cells by inhibiting proliferation and EMT." (PMID 40296944, 2025). "One example is observed in ovarian cancer, in which NUMB inhibits cell proliferation, invasion, and EMT." (PMID 37566749, 2023). "Given that both MSI-1 and MSI-2 are negatively correlated with NUMB and positively correlated with NOTCH-3 in our analyses, this seems applicable to ovarian cancer as well." (PMID 34768932, 2021). "In contrast to its role in fibrotic tissues, NUMB inhibits EMT in breast and ovarian cancer, partially by suppressing β-catenin signaling." (PMID 34124033, 2021).
bladder cancer (4 papers, 2014 to 2025). "Moreover, loss of NUMB has been linked to aggressive bladder cancer, thereby suggesting its function as a tumor suppressor gene in different cancer types." (PMID 40296944, 2025). "Further investigation revealed that METTL3/miR-146a-5p/NUMB/NOTCH2 signaling was positively correlated with recurrence, metastasis, and survival in bladder cancer patients, indicating that MLT sheds new light on therapeutic targets for recurrent bladder cancer treatment." (PMID 38017537, 2023). "Some cancer-associated DSGs in our result were reported in the other cancers but not reported in the bladder cancer yet, such as PDGFA, MACF1, ADD3 and NUMB." (PMID 24622401, 2014).
endometrial cancer (4 papers, 2018 to 2025). Primary or metastatic malignant neoplasm involving the endometrium (mucous membrane that lines the endometrial cavity). "This study demonstrates that significant NUMB protein expression is associated with aggressive clinicopathological features and poor prognostic outcomes in endometrial cancer." (PMID 40296944, 2025). "Significant levels of NUMB expression (NUMB 3) were associated with worse endometrial cancer outcomes, according to the findings of this study." (PMID 40296944, 2025). "This study demonstrates that significant NUMB expression (NUMB 3) is strongly associated with adverse clinicopathological features in endometrial cancer." (PMID 40296944, 2025). "The goal of this study was to investigate the association of NUMB protein expression with clinicopathological characteristics and prognostic outcomes in patients with endometrial cancer." (PMID 40296944, 2025). "TCGA analysis revealed significant associations between NUMB alterations and expression patterns in endometrial carcinoma, with copy number alterations showing a dose-dependent relationship with the expression levels." (PMID 41614791, 2025). "NUMB expression levels were significantly associated with mutational status in endometrial carcinomas." (PMID 41614791, 2025). "NUMB, a multifunctional protein, has been implicated in the tumorigenesis of endometrial cancer." (PMID 40296944, 2025). "The comprehensive bioinformatics analyses establish NUMB as a central hub protein in endometrial pathology, with significant prognostic value in endometrial cancer." (PMID 41614791, 2025). "Previous studies have shown that NUMB expression is elevated in endometrial cancer tissues compared to normal tissues and is predominantly localized in the nucleus, with some presence in the plasma membrane." (PMID 40296944, 2025). "Experimental evidence further suggests that NUMB overexpression induces apoptosis in Ishikawa endometrial cancer cells, whereas NUMB inhibition enhances cell proliferation, and there is evidence that it acts as a tumor suppressor." (PMID 40296944, 2025). "The aim of the present study is to correlate the expression of NUMB protein with clinical, histopathological parameters, and prognosis in endometrial cancer." (PMID 40296944, 2025). "This systems-level approach demonstrates that NUMB alterations have implications extending beyond adenomyosis to endometrial cancer prognosis and survival outcomes." (PMID 41614791, 2025). "A study using the Cancer Genome Atlas (TCGA) examined NUMB and its homolog NUMBL across multiple tumor types, including endometrial cancer, and found that NUMBL expression was associated with poorer prognosis." (PMID 40296944, 2025). "In vitro research has also shown that NUMB overexpression induces apoptosis in endometrial cancer cells, whereas its knockdown increases their proliferation." (PMID 40296944, 2025). "To assess the clinical significance of NUMB alterations in endometrial pathology, we performed Kaplan–Meier survival analysis using TCGA endometrial carcinoma data." (PMID 41614791, 2025). "Kaplan–Meier survival analysis demonstrated that endometrial carcinoma patients with NUMB alterations had significantly better overall survival compared to unaltered cases (p = 9.119 × 10−3), with 92% vs. 73% survival at 100 months." (PMID 41614791, 2025). "This dual functionality becomes crucial when linking adenomyosis findings to endometrial cancer survival data, as NUMB alterations may confer protective effects in malignant contexts while contributing to invasive behavior in benign conditions." (PMID 41614791, 2025). "It would be plausible to use molecular methods in order to select or exclude potential candidates for fertility-sparing treatment of endometrial cancer, and NUMB could also be the subject of oncofertility research in future studies." (PMID 40296944, 2025).
endometrial cancer (continued). "The observed alterations in NUMB expression and copy number in endometrial carcinomas support our hypothesis that NUMB dysregulation plays a role in endometrial pathogenesis, including adenomyosis, and may contribute to disease progression." (PMID 41614791, 2025).
glioma (4 papers, 2014 to 2024). A benign or malignant brain and spinal cord tumor that arises from glial cells (astrocytes, oligodendrocytes, ependymal cells). "Noteworthy, NUMB exerts its major effect for maintaining normal neural and glioma stem cell state by inhibiting NOTCH1 signaling, which allows brain tumor growth and glioma stem cell proliferation." (PMID 31963852, 2020). "To evaluate this possibility we analyzed NUMB expression in normal and glioma tumors and correlated its expression with patients’ survival data using the GlioVis portal database." (PMID 30890698, 2019). "This is consistent with a previous study in which overexpression of NUMB by deletion of Musashi, a known repressor of NUMB translation, resulted in glioma cells arresting in M phase." (PMID 24980814, 2014).
astrocytomas (3 papers, 2014 to 2018). "On the other hand, overexpression of NUMB was found in astrocytomas and cervical squamous carcinoma cells, suggesting that NUMB also possesses oncogenic potential." (PMID 24980814, 2014). "In accordance with this hypothesis, NUMB levels are higher in astrocytomas and cervical squamous carcinoma cells, and the positive effect of NUMBL over SHH signaling can also promote tumor progression." (PMID 29507685, 2018).
Oral Carcinoma (3 papers, 2013 to 2025). "This study demonstrated that NUMB is a novel binding partner of MCT1 and MCT4 and that the miR-31-NUMB-MCT1/MCT4 regulatory cascade is present in oral carcinoma." (PMID 34769160, 2021).
triple-negative breast carcinoma (3 papers, 2016 to 2025). An invasive breast carcinoma which is negative for expression of estrogen receptor (ER), progesterone receptor (PR), and human epidermal growth factor receptor 2 (HER2). "The expression of NUMB is deficient or reduced in triple-negative breast cancer (TNBC), and low NUMB expression in CSCs is associated with reduced distant metastasis-free survival." (PMID 34374886, 2021).
Alzheimer disease (2 papers, 2023 to 2025). A progressive, neurodegenerative disease characterized by loss of function and death of nerve cells in several areas of the brain leading to loss of cognitive function such as memory and language. "NUMB has also been linked to Alzheimer’s disease, where it plays a role as an adaptor of amyloid precursor protein (APP), an essential protein in the pathogenesis of the disease." (PMID 36672267, 2023). "Ex3sk-specific immunofluorescent labeling of NUMB in the parietal cortex of Alzheimer’s disease (AD) patients and age matched controls indicated significantly elevated expression in the AD samples." (PMID 39863103, 2025). "In this work, we review the various roles of NUMB in the cell as an adaptor, polarization agent, and endocytic protein, and how these functions are involved in the development of pathologies such as Alzheimer’s disease and cancer." (PMID 36672267, 2023). "The collapsin response mediator protein 2 (CRMP2) is involved in NUMB-mediated endocytosis, and its increased phosphorylated state is considered an early sign of Alzheimer’s disease." (PMID 36672267, 2023). "Because of its adaptor role, NUMB has also been proposed as a therapeutic target, not only in different types of cancer but also in various pathologies such as Alzheimer’s disease, among others." (PMID 36672267, 2023). "Recent studies have suggested NUMB as a possible biomarker for prognosis and/or response to certain therapies for cancer, Alzheimer’s disease, and other pathologies, with potential clinical applications." (PMID 36672267, 2023). "Due to its role in maintaining cellular homeostasis, it has been suggested that NUMB may be involved in various human pathologies such as cancer and Alzheimer’s disease." (PMID 36672267, 2023). "Furthermore, the proposal of NUMB as a possible therapeutic target for Alzheimer’s disease has been taken even further, with the possibility that the therapeutic value of the isoforms could be differentiated." (PMID 36672267, 2023). "Regarding Alzheimer’s disease, pharmacological modulation of APP by downregulating NUMB has been proposed as a novel therapeutic strategy." (PMID 36672267, 2023).
atherosclerosis (2 papers, 2019 to 2022). A disease characterized by the build-up of fatty material and calcium deposition in the arterial wall resulting in partial or complete occlusion of the arterial lumen. "Integrins are the main family of migration-promoting receptors that regulate cell migration and promote the development of atherosclerosis by mediating cells and the extracellular matrix, whereas integrin-stimulated cell migration requires the participation of NUMB." (PMID 35529060, 2022). "It has recently been reported that the levels of miR-146-5p and its targets NUMB and DLST are strongly linked to TMAO levels and may be involved in the progression of atherosclerosis." (PMID 31741723, 2019).
chronic myeloid leukemia (2 papers, 2023 to 2025). "Increased expression of SMO, a key component of the Hedgehog pathway, has been found to increase both the number of stem cells and the spread of chronic myeloid leukemia by decreasing NUMB levels in patients." (PMID 36672267, 2023). "This study revealed deregulation of asymmetric stem cell division markers during chronic myeloid leukemia (CML) progression, with pronounced downregulation of five key genes—CD63, SELL, NUMB, HK2, and LAMP2—during blast crisis compared to the chronic phase." (PMID 40868343, 2025).
coronary artery disease (2 papers, 2019 to 2022). "Multivariate logistic regression evaluation found that lower NUMB expression was correlated with an increased risk of coronary artery disease." (PMID 35529060, 2022).
lung squamous cell carcinoma (2 papers, 2023 to 2024). "However, in lung squamous cell carcinoma, NUMB may promote cell proliferation." (PMID 38791918, 2024).
malignant pleural mesothelioma (2 papers, 2018 to 2022). A malignant neoplasm that arises from mesothelial cells in the pleura and shows a diffuse growth pattern. "The role of NUMB as a tumor suppressor gene has been widely characterized, revealing that lower NUMB levels are associated with a worse prognosis in malignant pleural mesothelioma." (PMID 29507685, 2018).
neuroblastoma (2 papers, 2019 to 2024). Neuroblastoma (NB) is the most common solid, extracranial childhood tumor. "We verified the endogenous NUMB–ALK interaction by co-immunoprecipitation (Co-IP) in the IMR-5 cells, a neuroblastoma cell line expressing wild-type ALK." (PMID 30726988, 2019).
oral squamous cell carcinoma (2 papers, 2016 to 2018). "miR-146a induces an oncogenic phenotype and tumorigenesis of oral squamous cell carcinoma by directly targeting the 3’-UTR of NUMB." (PMID 27824903, 2016).
thyroid cancer (2 papers, 2023 to 2024). "Because NUMB can significantly inhibit the NOTCH pathway, hsa_circ_0058124 upregulates NUMB expression through a miR-218-5p sponge, thereby inhibiting the NOTCH pathway and promoting the invasion ability of thyroid cancers." (PMID 38316961, 2024).
ZIKV infection (2 papers, 2019 to 2024). "This induction also regulated the expression of Bcl2 and NUMB, mimicking the effect observed in ZIKV infection." (PMID 39347716, 2024). "In particular, we found that miR34c, like ZIKV infection, reduces NUMB expression in both NSCs and GSCs." (PMID 30890698, 2019). "Moreover, the expression of miR34c reduces NSCs and GSCs cell growth and regulates both Bcl2 and NUMB expression, mimicking the same effect observed in the ZIKV infection." (PMID 30890698, 2019). "ZIKV infection also induced inhibition of the development of genes responsible for tumor cell maintenance and proliferation, such as NOTCH (a signaling protein that regulates cellular development and maintenance of stem cells) and NUMB (a negative regulator protein of the NOTCH pathway)." (PMID 39347716, 2024).
acute leukemia (1 paper, 2013). A clonal (malignant) hematopoietic disorder with an acute onset, affecting the bone marrow and the peripheral blood. "Thus we hypothesize that ERG overexpression may repress NUMB possibly through negative regulation of AKT/PI3K in acute leukemia." (PMID 23300998, 2013).
acute myeloid leukemia (1 paper, 2013). Acute myeloid leukemia (AML) is a group of neoplasms arising from precursor cells committed to the myeloid cell-line differentiation. "For NUMB, a potent inhibitor of NOTCH1, its expression was shown to be significantly down regulated in acute myeloid leukemia." (PMID 23300998, 2013).
acute myocardial infarction (1 paper, 2022). Necrosis of the myocardium, as a result of interruption of the blood supply to the area. "Peripheral blood NUMB gene expression was associated with an increased risk of acute myocardial infarction (AMI)." (PMID 35529060, 2022). "Our study's goal was to find out acute myocardial infarction (AMI) patients' NUMB gene expression patterns and to evaluate its role as a diagnostic marker for AMI detection." (PMID 35529060, 2022).